LDHA (lactate dehydrogenase A)
Diseases named in the same sentence as LDHA in open-access papers (continued):
Sharing a sentence is not in itself a finding about the gene and the disease.
melanoma (continued). "Using that approach, the proteomic comparison of melanoma-derived plasma exosomes with remaining non-melanoma plasma exosomes showed an increase in signaling and immune regulating proteins including LDHA, NOTCH2 and thrombospondin-1 among others." (PMID 36704194, 2022). "Of note, a negative correlation between LDHA expression and T cell activation markers was described in in human melanoma patients." (PMID 33499083, 2021). "Without canonical expression of LDHA, LDHi failed to control melanoma growth in mice." (PMID 39225102, 2024). "Additionally, the ECAR analysis also indicated that LDHA not LDHA Y10F transfection significantly increased the ECAR of melanoma cells compared with the LDHA knockdown group." (PMID 37480145, 2023). "Elevated lactate dehydrogenase A (LDHA) is a well-known negative prognostic factor in melanoma." (PMID 36077374, 2022). "However, the LDHB expression did not change in LDHA knockout mouse melanoma (B16-F10) cells, as analyzed using Western blotting." (PMID 31921691, 2019). "Moreover, both histone lactylation inhibitors (oxamate and 2-DG) and LDHA/B inhibition have resulted in a dramatic decreased histone lactylation levels in the promoter region of ALKBH3, which subsequently abrogates the RNA and protein levels of ALKBH3 in all tested melanoma cells." (PMID 38118002, 2024). "In human colon adenocarcinoma and murine melanoma cells, neither LDH-A nor LDH-B knockout strongly reduced lactate secretion, whereas the double knockout (LDHA/B-DKO) fully suppressed LDH activity and lactate secretion." (PMID 35565435, 2022). "Mice lacking IFN-γ and IFN-γR1 failed to counteract tumor growth in mouse melanoma cells, possessing both IFN-γ and IFN-γR1, regardless of LDHA status." (PMID 28798748, 2017). "In addition to the balanced upregulation of these two metabolic pathways, advanced melanoma cells acquire the ability to utilize non-glucose sources, such as lactate (LDHA and MCT1 upregulation), as well as the ability to prevent buildup of acid that may prevent tumor growth (MCT4 upregulation)." (PMID 23043612, 2012).
glioma (99 papers, 2013 to 2026). A benign or malignant brain and spinal cord tumor that arises from glial cells (astrocytes, oligodendrocytes, ependymal cells). "In high-grade gliomas, including glioblastoma (GBM), LDHA expression is significantly elevated compared with low-grade gliomas, and its overexpression has been linked to resistance to radiotherapy and chemotherapy, particularly temozolomide." (PMID 40565174, 2025). "The Kaplan–Meier survival curve analysis of the association between LDHA/MCT4 and mortality indicated that glioma patients with lower LDHA and MCT4 expression had prolonged survival time." (PMID 35864093, 2022). "IDH‐mutated gliomas, which are of better prognosis than IDH1wt gliomas, express lower levels of LDHA." (PMID 36278433, 2022). "We previously demonstrated that cyclin G2 associated with LDHA and inhibited Y10 phosphorylation of LDHA in glioma cells, though the underlying mechanism remained elusive." (PMID 34452627, 2021). "Another study showed that the loss of DNA methylation of LDHA was associated with certain malignant clinicopathological features such as a high glycolytic phenotype in gliomas." (PMID 34393804, 2021). "IDH1/2 mutation-driven downregulation of LDHA prevents glycolytic switch (Warburg effect) and limits the growth of gliomas." (PMID 29439493, 2018). "Lower expression levels of LDHA in IDH1MUT glioma were associated with hypermethylation of its promoter." (PMID 28467784, 2017). "An example is the repression of LDHA expression in gliomas carrying IDH1/2 mutations." (PMID 37546420, 2023). "Finally, when we overexpressed miR-200b in glioma cells, the increased cell glycolysis, proliferation and invasion caused by LDHA were inhibited." (PMID 27374173, 2016). "In this study, by downloading glioma-related datasets from TCGA, CGGA, and GEO, we analyzed the expression, prognosis, and diagnostic values of LDHA and SLC16A1 in LGG cohorts." (PMID 40782248, 2025). "Collectively, these findings demonstrate that SMC4 promotes glycolysis in glioma cells by upregulating LDHA, thereby providing metabolic energy support for malignant proliferation." (PMID 40933894, 2025). "Glioma cells exhibit a glycolytic phenotype with upregulated LDHA, PKM2, and MCTs, resulting in elevated intracellular and extracellular lactate levels." (PMID 41463052, 2025). "Analyses of The Cancer Genome Atlas (TCGA) and Chinese Glioma Genome Atlas (CGGA) databases revealed that GBM patient prognosis was negatively correlated with LDHA expression." (PMID 40093910, 2025). "The observation that inhibitors block EV homing provides novel insights into many therapeutic opportunities to target LDHA/LDHB in glioma treatment." (PMID 40093910, 2025). "Aerobic glycolysis (the Warburg effect) is a hallmark of glioma energy metabolism, and our data link SMC4 to this process through regulation of LDHA." (PMID 40933894, 2025). "In glioma, lactate production is primarily mediated by lactate dehydrogenase A (LDHA), while the efflux is mainly facilitated by monocarboxylate transporter 1 (MCT1)." (PMID 38576043, 2024). "Kaplan–Meier analysis results revealed that high LDHA expression correlated with poor overall survival (OS) among glioma patients in both TCGA and CGGA datasets." (PMID 38576043, 2024). "LDHA expression correlates with tumor grade, as GBM exhibits LDHA higher levels compared with low-grade gliomas and portends a poor prognosis in GBM patients." (PMID 39545414, 2024). "Studies have reported that lactate dehydrogenase A (LDHA)-mediated lactate production increases in glioma, especially in IDH wild-type glioma and monocarboxylate transporter 1 (MCT1) plays a prominent role in transmembrane transport of lactate." (PMID 38576043, 2024). "To evaluate the levels of lactate metabolism in glioma, we analyzed the mRNA levels of LDHA and MCT1 (referred as SLC16A1 at the mRNA level) using bulk RNA-seq data from the TCGA and CGGA datasets." (PMID 38576043, 2024).
glioma (continued). "Similar to the TCGA datasets, all 11 genes exhibited WHO grade-dependent expression in glioma samples, with 6 upregulated (LDHA, MIF, NAMPT, PGK1, SAT1, and PLOD2) and 5 downregulated genes (ALDOC, ABAT, ADCY2, GALNT13, and PDE8B)." (PMID 38989284, 2024). "Our analysis revealed that the expression of LDHA in glioma was significantly elevated compared to normal tissues." (PMID 38576043, 2024). "We also found HIF-1α induced in hypoxia cultured glioma cells, and the expressions of LDHA and BCAT1 were also increased." (PMID 37298317, 2023). "Circadian genes CLOCK and BMAL1 are found to regulate expression of IL-1ß and LDHA in gliomas, with suppression of CLOCK and BMAL1 leading to a reduction in LDHA and IL-1ß levels." (PMID 38173841, 2023). "It has been demonstrated that lactate induces migration and cellular invasion in high-grade glioma which overexpresses higher LDHA levels through transforming growth factor β2 (TGFβ2)/integrin αvβ3/MMP2 signaling." (PMID 38139462, 2023). "There is a similar result reported in the mutant isocitrate dehydrogenase (IDHmut) glioma that the LDHA promoter showed increased methylation, leading to its low expression." (PMID 36518315, 2022). "The expression values of AEBP1, F3, FLNC, IGFBP2, and LDHA were compared among normal brain tissue, low-grade gliomas (LGG), and GBM." (PMID 35783254, 2022). "The knockdown of LDHA decreased the cell growth by impairing cell cycle progression and triggering apoptosis in glioma cell lines." (PMID 35783254, 2022). "The results showed that glioma tissues have higher expression of LDHA, HLF1A, SLC16A1, and MRS2 and lower expression of LDHB and SLC25A12 compared with paracancerous tissues." (PMID 36698888, 2022). "For instance, lactate induces TGF-β2 expression in glioma cells and knockdown of lactate dehydrogenase A (LDHA), an enzyme that catalyzes lactate production, downregulates TGF-β2 levels." (PMID 35359452, 2022). "It was indicated that miR-9 has a negative correlation with the ANXA2P2 mRNA target, and overexpression of this miRNA suppresses the cell proliferation and aerobic glycolysis of glioma cells by binding to LDHA 3′UTR." (PMID 34947885, 2021). "Conclusively, these findings demonstrated that cyclin G2 suppresses proliferation, migration, invasion, glycolysis and promotes apoptosis of glioma cells by inhibiting Y10 phosphorylation of LDHA." (PMID 34452627, 2021). "Meanwhile, we observed that PKM2, c-myc, GLUT1, and LDHA expression of the two glioma cell lines reverted at 24 h." (PMID 34744739, 2021). "Recent studies discovered that other glycolytic enzymes, such as PKM2 and lactate dehydrogenase A (LDHA), are also upregulated in glioma." (PMID 34681857, 2021). "Cyclin G2 inhibited proliferation, migration, invasion capacity, and glycolysis and promoted apoptosis glioma cells via suppressing Y10 phosphorylation of LDHA." (PMID 34452627, 2021). "MTS analysis revealed that LDHA knockdown impaired the proliferation, whereas restoring LDHA WT rescued proliferation in glioma." (PMID 34452627, 2021). "We also measured protein expression levels of key glycolytic enzymes HK2 and LDHA in glioma cells, as well as enzyme activity of LDHA." (PMID 32774168, 2020). "LINK-A, the upregulated lncRNA in the glioma cells, has been shown to regulate expression of lactate dehydrogenase A (LDH-A), thus enhancing glycolysis and proliferation in these cells." (PMID 33123468, 2020). "In the post-transcriptional regulation, a miR-200b inversely correlates with the LDHA level in gliomas." (PMID 31035592, 2019). "Our results also support previous reports that show that IDH1MUT gliomas silence LDHA expression through hypermethylation of its promoter resulting in a low LDHA/LDHB ratio compared with IDH1WT glioma or normal brain tissue." (PMID 28467784, 2017). "Among the activated genes, some encodes metabolic enzymes, such as lactate dehydrogenase A (LDHA), which can in turn induce a modification of glioma cell metabolism and behavior." (PMID 29261132, 2017).
glioma (continued). "Taken together, these results indicated that LDHA was up-regulated and promoted cell proliferation and invasion in glioma." (PMID 27374173, 2016). "Here, we investigated the expression and function of LDHA and the regulation of miR-200b to LDHA in glioma." (PMID 27374173, 2016). "miR-200b was found to be down-regulated in glioma samples, which was inversely correlated with LDHA expression." (PMID 27374173, 2016). "Taken together, these results indicated that LDHA was a direct target of miR-200b and was negatively correlated with miR-200b in glioma." (PMID 27374173, 2016). "Taken together, these results indicated that LDHA-induced glycolysis, cell proliferation and invasion can be inhibited by miR-200b in glioma cells." (PMID 27374173, 2016). "Then differences in metabolic parameters were examined and we found that overexpression of LDHA largely promoted aerobic glycolysis in glioma cells, e.g., increased glucose uptake and lactate production." (PMID 27374173, 2016). "Lactate production by LDHA activates TGF‐β in glioma 6; therefore, it is possible that LDHA also activates TGF‐β to promote evasion of the immune response." (PMID 26269128, 2016). "We found that high expression of LDHA was correlated with higer glioma histopatholgy grade(P=0.004)." (PMID 27374173, 2016). "Repression of LDHA by miR-200b suppressed the glycolysis, cell proliferation and invasion of glioma cells." (PMID 27374173, 2016). "Futher we checked the correlation between expression of LDHA and its clinicopathological parameters in that 73 glioma samples." (PMID 27374173, 2016). "The results indicated that overexpression of LDHA in U87 and U251 cells markedly increased the viability of glioma cells and promoted cells toform much more colonies than the control group." (PMID 27374173, 2016). "The effects of LDHA alteration on cell viability and growth were evaluated in glioma cells using MTT and colony formation assays." (PMID 27374173, 2016). "Taken together, these results demonstrate that LDHA acts as a tumor promoter in glioma and can be targeted by miR-200b." (PMID 27374173, 2016). "Then we detected the expression level of LDHA in 73 glioma samples and 30 unmatched normal cerebrum samples and found that the expression level of LDHA in glioma was significantly higher than that in normal samples." (PMID 27374173, 2016). "Here, we investigated the expression pattern and function of LDHA in glioma and explored the possible correlation between miR-200b and LDHA in glioma." (PMID 27374173, 2016). "The comparison of the LDHA expression level of GBMs and other gliomas demonstrated that LDHA expression is stronger in GBMs than in other gliomas." (PMID 23456655, 2013). "To determine the source of the increased levels of lactic acid, we examined the expression of LDHA (lactate dehydrogenase-A), which produces lactic acid from pyruvate, in all glioma samples analyzed." (PMID 23456655, 2013). "In particular, silencing LDHA could inhibit cell proliferation and enhance the chemosensitivity of glioma cells to temozolomide." (PMID 40244246, 2025). "Specific deletion of promoter methylation of glycolytic genes, particularly lactate dehydrogenase A (LDHA), results in the acquisition of a hyperglycolytic phenotype, leading to lactate accumulation that correlates with the grade of glioma, enhanced proliferative invasiveness, and poorer survival." (PMID 40244246, 2025). "SLC16A1 overexpression and downregulation of LDHA have been validated in glioma cell lines." (PMID 40782248, 2025). "Targeting glycolysis‐associated proteins, such as lactate dehydrogenase A (LDHA), glucose transporter type 1 (GLUT1), and pyruvate kinase M2 (PKM2), may impede the migration and invasion of glioma cells." (PMID 38332637, 2024).
glioma (continued). "To underscore the pivotal role of lactate in mediating the polarized effects of macrophages, we treated glioma cells with an LDHA inhibitor, sodium oxamate (SO), to inhibit lactate production, and an MCT inhibitor, α-cyano-4-hydroxycinnamate (CHC), to reduce lactate efflux, respectively." (PMID 38576043, 2024). "Importantly the overexpression of LDHA and overproduction of lactate in gliomas and other tumors has been established as a potential biomarker of malignity." (PMID 38139462, 2023). "In addition, if LDHA did oxidize glyoxylate in glioma cells, the generation of cytoplasmic NADH from glyoxylate oxidation would conceivably impede glycolysis, which is a critical energy-generating pathway for glioma cells." (PMID 37546420, 2023). "Not surprisingly, the loss of the promoter methylation of LDHA and the higher LDHA expression were evidenced in the IDHnut aggressive glioma." (PMID 36518315, 2022). "Since LDHA expression is promoted by hypoxia, low levels of LDHA in gliomas that were cultivated under standard conditions in the presence of oxygen may be attributable to an oxygenated environment." (PMID 36142793, 2022). "Western blotting and qRT-PCR were used to show that GLUT1 and LDHA expression could be significantly restored in glioma cells with PKM2 overexpression." (PMID 34744739, 2021). "Consistent with our analysis results, a study showed that the expression of LDHA is relevant to the malignancy of tumors and could affect the proliferation, apoptosis, and chemical sensitivity of temozolomide in glioma cells." (PMID 35127693, 2021). "A previous study reported that glioma cells with IDH1 mutation produce 2-hydroxyglutarate, which promotes HIF-1α degradation, accompanied by the downregulation of glycolysis-related genes including SLC2A1, PDK1, LDHA, and SLC16A3." (PMID 33627136, 2021). "Lactate dehydrogenase A is underexpressed in low-grade gliomas as a result of promoter methylation." (PMID 33397920, 2021). "Meanwhile, the KLHDC8A expression which induced by glucose is dependent of LDHA in glioma cells." (PMID 32851798, 2020). "Finally, our data suggest that the detected metabolic heterogeneity (the high mTORC2 complex activity, enhanced expression of Rictor, p-Akt, p-S6, CPT1A and LDHA enzymes in glioma cases) is a very promising combination target." (PMID 31187466, 2020). "Consequently, in current study, we monitored HK2 and LDHA expression, as well as LDHA enzyme activity to analyze aerobic glycolysis of glioma cells." (PMID 32774168, 2020). "As a matter of fact, glioma tumors and cells harboring IDH1mut are characterized by lower intracellular lactate levels compared to IDH1wt, probably due to hypermethylation of the lactate dehydrogenase A (LDHA) gene promoter driven by 2-HG increase." (PMID 32824685, 2020). "Thus, repression of LDHA by miR-200b suppresses the glycolysis, cell proliferation, as well as invasion of glioma cells." (PMID 31035592, 2019). "Furthermore, mutant IDH1 decreases the HIF-1α-responsive gene, LDHA, which is essential for glycolysis and is overexpressed in cancers, through IDH-mutant-induced methylation of LDHA promoter, finally limiting the rapid cell growth of high-grade glioma." (PMID 31450721, 2019). "GLS and LDHA are metabolic enzymes that participate in biological progression of IDH-mutant glioma; however, the role of AS of GLS and LDHA in glioma remains unclear." (PMID 31729991, 2019). "Indeed, we observed significant negative correlations between ClockLoss and HIF-1A targets (CA9, VEGFA and LDHA) in glioma." (PMID 31014368, 2019). "In IDH1WT glioma, we observed a striking overexpression of LDHA relative to IDH1MUT glioma." (PMID 28467784, 2017). "To verify whether LDHA is a direct target of miR-200b we performed luciferase reporter assays in glioma cell line U251." (PMID 27374173, 2016). "Moreover, we observed a down-regulation of miR-200b in glioma samples, which was inversely correlated with LDHA levels." (PMID 27374173, 2016).